EDN3 (endothelin 3)
Description:
Endothelins are endothelium-derived vasoconstrictor peptides.
Synonyms: ET-3; PPET3; ET3; HSCR4; WS4B
Tractability: Small molecule: a structure with a bound ligand is known. Antibody: its Gene Ontology location is reachable by antibodies, with high confidence; UniProt places it where antibodies can reach, with medium confidence; UniProt predicts a signal peptide or a membrane-spanning region.
Gene: Protein-coding gene on chromosome 20 (59,300,415 to 59,325,992, forward strand). Ensembl gene ENSG00000124205.
Subcellular location: Secreted
Pathways (Reactome):
Signal Transduction: G alpha (q) signalling events; Peptide ligand-binding receptors
Developmental Biology: Transcriptional and post-translational regulation of MITF-M expression and activity
Gene Ontology:
Molecular function: endothelin B receptor binding; hormone activity; signaling receptor binding
Biological process: artery smooth muscle contraction; cell surface receptor signaling pathway; neutrophil chemotaxis; peptide hormone secretion; positive regulation of cell differentiation; positive regulation of cell population proliferation; positive regulation of heart rate; positive regulation of hormone secretion; positive regulation of leukocyte chemotaxis; positive regulation of MAPK cascade; positive regulation of mitotic nuclear division; regulation of gene expression; regulation of systemic arterial blood pressure by endothelin; vasoconstriction; vein smooth muscle contraction; blood circulation; cell-cell signaling; intracellular calcium ion homeostasis; positive regulation of smooth muscle contraction; signal transduction; axon extension; axon guidance; neuron projection development; regulation of vasoconstriction
Cellular component: extracellular region
Genetic constraint (gnomAD): Loss-of-function variants: 9 observed, 22.56 expected, observed/expected ratio (o/e) 0.4, 90% interval 0.24 to 0.7. The upper end of that interval is the gene's LOEUF score, 0.7, which puts it in group 2 of 6, group 1 being the genes least tolerant of losing a copy. Missense variants: 327 observed, 324.45 expected, observed/expected ratio (o/e) 1.01, 90% interval 0.92 to 1.1. Synonymous variants: 133 observed, 133.12 expected, observed/expected ratio (o/e) 1, 90% interval 0.87 to 1.15.
Gene-disease validity (ClinGen):
ClinGen rates the evidence that EDN3 causes each of these diseases.
Waardenburg syndrome type 4B (autosomal recessive): Moderate. A subtype of Waardenburg syndrome type 4 (Waardenburg-Shah syndrome) caused by mutations in EDN3.
Waardenburg syndrome type 4B (autosomal dominant): Limited.
Homologues: Orthologues: chimpanzee EDN3 (99% identical), macaque EDN3 (81% identical), dog EDN3 (56% identical), rabbit EDN3 (54% identical), mouse Edn3 (54% identical), guinea pig EDN3 (51% identical), rat Edn3 (41% identical), tropical clawed frog edn3 (34% identical), zebrafish edn3b (20% identical). Paralogues in human: EDN2 (21% identical), EDN1 (19% identical).
Diseases named in the same sentence as EDN3 in open-access papers:
EDN3 is named in the same sentence as 84 diseases in open-access papers, as found by Europe PMC text mining. Sharing a sentence is not in itself a finding about the gene and the disease. The quoted sentences say what the papers report.
Hirschsprung disease (16 papers, 2009 to 2025). Hirschsprung disease (HSCR) is a congenital intestinal motility disorder that is characterized by signs of intestinal obstruction due to the presence of an aganglionic segment of variable extent in the terminal part of the colon. "Several genes and gene loci including genes encoding endothelin 3 or endothelin receptor B are found to be responsible for aganglionosis, a developmental abnormality of the enteric nervous system, in Hirschsprung disease." (PMID 36213246, 2022). "Moreover, in the WS4 cases associated with EDNRB and EDN3 pathogenic variants, the characteristic presentation of Hirschsprung disease caused by enteric nervous system disorder was inconclusive." (PMID 41516007, 2025). "Consistent with this possibility, endothelin-3, a gene implicated in Hirschsprung’s disease, is important for maintaining a pro-proliferative environment for the vagal neural crest in the avian hindgut and is required for sacral neural crest colonization in the murine hindgut." (PMID 37877560, 2023). "The idea answer is: Coding sequence mutations in RET, GDNF, EDNRB, EDN3, and SOX10 are involved in the development of Hirschsprung disease." (PMID 40766492, 2025). "Recent studies detected significant thymic involution, splenic lymphopenia and suppression of T and B lymphopoiesis in murine models of Hirschsprung’s disease either with endothelin receptor B deletion or endothelin 3-null mice." (PMID 36213246, 2022). "In addition to conditional mouse mutants in which NCCs are depleted of ß1-integrins, several mouse models of Hirschsprung disease (edn3/EDNRB63, Sox1013) display a delay, by about one day, in the chronology of ENCC migration with respect to the wild type." (PMID 26887292, 2016). "Mutations in the genes encoding the EDN receptor B (EDNRB), its ligand EDN3, and the transcription factor SOX10 cause Waardenburg-Shah syndrome (also known as Waardenburg syndrome type IV), comprised of pigment cell abnormalities and Hirschsprung’s disease." (PMID 24040226, 2013). "Interestingly, in congenital sensorineural deafness, the other major EDN3-EDNRB phenotype that with Hirschsprung disease defines Waardenburg-Shah syndrome type IV, the penetrance of hearing impairment in ICR background Edn3 or Ednrb mutant mice is variable (approx. 50%)." (PMID 39641974, 2024). "Moreover, other genes involved in the endothelin signaling pathway (endothelin B receptor gene, EDNRB and endothelin 3 gene, EDN3) have been implicated in Hirschsprung’s disease and could be considered as candidate genes for CCH syndromes and sleep apnea." (PMID 19794884, 2009). "Our findings implicate a dual lineage origin for the ENS with mechanistically distinct features, and illuminate the consequences of Edn3 and GDNF signaling that account for Hirschsprung disease when either is compromised." (PMID 39641974, 2024). "No alteration in the gene dosage was observed in the other three genes related to Hirschsprung disease (GDNF, EDN3 and ZFHX1B) in all controls, thyroid samples and thyroid cell lines." (PMID 31288802, 2019). "The Hirschsprung’s disease (or colonic aganglionosis) the typical signal signals, neurotrophic factor (GDNF)-family ligands transduced by Ret and GFRa1 receptors and on endothelin 3 (ET3)/endothelin receptor B (ETRB) pathway, are absent." (PMID 32244473, 2020). "If true, this explanation for the expression of EDN3 in our cultures and its down-regulation by RA supports an interaction of RA and EDNRB signaling in the expression of Hirschsprung’s disease, albeit in a non-neural crest autonomous fashion." (PMID 24040226, 2013).
Waardenburg syndrome (15 papers, 2011 to 2025). A disorder characterized by varying degrees of deafness and minor defects in structures arising from neural crest, including pigmentation anomalies of eyes, hair, and skin. "In roof/epithelial (CD−M1), Myo6 and Actg1 were associated with nonsyndromic hearing loss (NSHL), Hsd17b4 with Perrault syndrome, Ednrb and Edn3 with Waardenburg syndrome, and Actg1 with Baraitser–Winter syndrome." (PMID 39684410, 2024). "The p.Arg96Cys variant of the EDN3 gene is described in the literature to be associated with Waardenburg syndrome." (PMID 40626131, 2024). "Waardenburg syndrome is genetically heterogeneous and results from mutations in Sox10, Pax3, Mitf, Snai2, Ednrb, and Edn3, as well as many cases with unidentified mutations." (PMID 32912160, 2020). "However, in the phenotypically similar Waardenburg syndrome in humans, these phenotypes are associated with EDN3, SOX10, and EDNRB." (PMID 32616020, 2020). "Genetic studies suggest that Waardenburg syndrome is caused by mutations of PAX3 and other genes such as MITF, SOX10, EDN3, EDNRB and SNAI21,9,13,35–37." (PMID 38278860, 2024). "Six genes involved in Waardenburg syndrome include PAX3 (encoding the paired box 3 transcription factor), MITF (microphthalmia-associated transcription factor), EDN3 (endothelin 3), EDNRB (endothelin receptor type B), SOX10 (encoding the Sry bOX10 transcription factor), and SNAI2 (snail homolog 2)." (PMID 35790984, 2022). "Thus, possible candidates for white coat colour (KIT on BTA6, KITLG on BTA5, PMEL on BTA5, TYR on BTA29) and other Waardenburg syndromes (WS) including PAX3 (WS1, WS3; on BTA2), EDNRB (WS4a; on BTA12), EDN3 (WS4b; on BTA13) and SOX10 (WS2e, WS4c; on BTA5) could be clearly excluded." (PMID 22174915, 2011). "Although the Waardenburg syndrome genes PAX3, SOX10, MITF, EDN3 and EDNRB were not dramatically affected at the mRNA level, expression of the piebaldism gene KIT was significantly down-regulated upon loss of YY1." (PMID 22570637, 2012).
melanoma (11 papers, 2015 to 2025). A malignant, usually aggressive tumor composed of atypical, neoplastic melanocytes. "Moreover, yet another Hirschsprung-associated gene, EDN3, has also been linked to melanoma invasiveness." (PMID 25679399, 2015). "EDN3 has been found upregulated in glioblastoma stem cells, melanoma, and breast cancer and similarly to NLGN4X, promotes tumor proliferation and invasiveness." (PMID 34572907, 2021). "Endothelin 3 (END3) is reported to participate in the progression of several cancers including malignant melanoma, cervical cancer, and colon cancer." (PMID 33441161, 2021). "Then, researchers transplanted melanoma cells into wild-type, EDN3-, or ECE2-deficient transgenic zebrafish and verified that variation in the tumor microenvironment exerts a tremendous impact on melanoma development and metastasis." (PMID 33644052, 2021). "Among these various factors, our data indicate that microenvironmental EDN3 is uniquely capable of inducing a phenotype switch to yield melanoma cells that are both proliferative and differentiated across both zebrafish and human conditions." (PMID 28181494, 2017). "As its inhibition may induce cell arrest, EDN3 gene has been suggested as a new therapeutic option for glioblastoma, melanoma and more in general for cancer patients overexpressing it." (PMID 34572907, 2021). "We hypothesized that inactivation of EDN3 in the microenvironment would abrogate phenotype switching in the nearby melanomas." (PMID 28181494, 2017). "We focused on the potential prognostic value of EDN3, CLEC4E, SRPX2, KIR2DL4, UBE2L6, and IFIT2 as immune scores for melanoma patients." (PMID 34660598, 2021). "They conjugated iron-carrying CPNPs with the endothelin 3 (EDN3-CPNP), which specifically targets the melanoma endothelin-B receptor (EDNRB), and showed enhanced melanoma tumor targeting and tumor cell killing effects." (PMID 34796174, 2021). "Here the authors identify EDN3, and its synthetic enzyme ECE2, as a regulator of melanoma plasticity in the microenvironment." (PMID 28181494, 2017). "We demonstrate that SCF-KIT signaling induces synthesis and secretion of endothelin-3 (ET3) in human umbilical vein endothelial cells and melanoma cells in vitro, gastrointestinal stromal tumors, human sun-exposed skin, and myenteric plexus of human colon post-fasting in vivo." (PMID 28880927, 2017). "Prevention of this differentiated cell state via EDN3/ECE2 inactivation doubles survival of the animals, suggesting that the acquisition of a differentiated cell state is necessary for metastatic success in melanoma, and can be prevented by interrupting microenvironment-melanoma cross-talk." (PMID 28181494, 2017).
colon carcinoma (9 papers, 2014 to 2023). "Similarly, loss of EDN2 or EDN3 in rat colon mucosa indicates their use as early marker for colon cancer." (PMID 32194414, 2020). "EDN3 is hypermethylated and down-regulated in human primary colon cancer and colon cancer cell lines, and overexpression of EDN3 can inhibit the invasion and migration of colon cancer cells." (PMID 36824133, 2023). "In a recent study, low to undetectable expression levels of EDN-2 and EDN-3 were found in human and rat colon cancers, but normal levels in matched control tissues." (PMID 32194414, 2020). "In a rat model of colonic tumorigenesis, EDN-2 and EDN-3 expression was lost several weeks before the onset of colon cancer." (PMID 32194414, 2020). "Intriguingly, epigenetic inactivation of ET-2 and ET-3 mRNA and protein was found in rat and human colon tumours and cancer cell lines, as a result of hypermethylation of EDN2 and EDN3 genes." (PMID 25131455, 2014). "Moreover, forced re-expression of EDN-2 and EDN-3 in human colon cancer cells led to inhibition of invasion and migration in vitro." (PMID 32194414, 2020). "In rat and human colon tumors, hypermethylation of EDN2 and EDN3 genes resulted in the epigenetic inactivation of ET-2 and ET-3 mRNA and corresponding protein." (PMID 26956245, 2016). "Thus, in human and rat colon cancer cell lines as well as in human primary colon cancers, there is down-regulation and hyper-methylation of the EDN-2 and EDN-3 genes." (PMID 32194414, 2020).
breast carcinoma (7 papers, 2009 to 2023). "Abnormalities caused by EDN3 were primarily described in breast cancer, as a result of which the survival and invasion ability of the cells changed." (PMID 34503158, 2021). "Attenuated EDN3 expression in breast carcinoma was also evident at the protein level (45%) in association with adverse patient outcome in univariate (P = 0.022) and multivariate (hazard ratio 2.0; P = 0.025) analyses." (PMID 19527488, 2009). "We therefore conclude that aberrant EDN3 methylation is a tumour-specific event and the predominant mechanism leading to EDN3 expression loss in breast cancer." (PMID 19527488, 2009). "After reverse selection, patient age, lymph node status, grade and EDN3 expression remained significant in the Cox model, with low EDN3 expression displaying a twofold elevated risk of dying from breast cancer (hazard ratio 1.98, 95% CI 1.09 to 3.61; P = 0.025)." (PMID 19527488, 2009). "To analyse whether loss of EDN3 expression in breast cancer is also evident on the protein level, we used a TMA comprising 150 invasive breast carcinomas and 44 normal breast tissue specimens." (PMID 19527488, 2009). "Moreover, a hypermethylated EDN3 promoter was also detected in 70% of breast carcinoma specimens in significant association with loss of EDN3 expression." (PMID 19527488, 2009). "Loss of EDN3 mRNA expression in breast cancer, as initially detected by array-based expression profiling, could be confirmed by Northern blot analysis (> 2-fold loss in 96%) and real-time PCR (> 2-fold loss in 78%)." (PMID 19527488, 2009). "Furthermore, EDN3 promoter hypermethylation was detected in 70% of primary breast carcinomas with significant association to loss of EDN3 mRNA expression (P = 0.005), whilst normal matched breast tissues revealed no EDN3 promoter methylation." (PMID 19527488, 2009). "To investigate a potential clinical relevance of EDN3 in breast cancer, we first analysed whether EDN3 protein expression is associated with clinicopathological parameters." (PMID 19527488, 2009). "Patients with high expression of EDN3 have long overall survival and disease-free survival, and EDN3 can be used as a biomarkers for early diagnosis and prognosis of breast cancer." (PMID 36824133, 2023). "Abnormal methylation of EDN3 gene is closely related to breast cancer, and hypermethylation of this gene can reduce or even silence its expression in breast cancer tissue." (PMID 36824133, 2023). "Here, we aimed at a first comprehensive analysis on EDN3 expression and its implication in human breast cancer." (PMID 19527488, 2009). "EDN3 mRNA expression in breast cancer was further validated by real-time polymerase chain reaction (PCR) (n = 77)." (PMID 19527488, 2009). "EDN3 is a frequent target of epigenetic inactivation in human breast cancer, potentially contributing to imbalanced EDN signalling commonly found in this disease." (PMID 19527488, 2009). "This showed a clear loss of EDN3 mRNA expression, as defined by a fold change (tumour versus normal) of greater than 2 (FC2), in 96% (48 of 50) of the analysed breast carcinoma samples and also in all three corresponding lymph node metastases (P < 0.001)." (PMID 19527488, 2009). "In contrast, most matched breast carcinomas showed diminished EDN3 mRNA expression both on the cDNA dot blot array and by real-time PCR analysis." (PMID 19527488, 2009). "A further TMA analysis revealed that EDN3 protein is abundantly expressed in normal breast whereas its expression is reduced in a large fraction of breast carcinomas." (PMID 19527488, 2009). "A tissue microarray was used to study EDN3 protein expression in breast carcinoma (n = 150) and normal breast epithelium (n = 44)." (PMID 19527488, 2009). "For 71 breast cancer specimens, both EDN3 methylation and EDN3 mRNA expression have been investigated in parallel." (PMID 19527488, 2009).